SOX2 (SRY-box transcription factor 2)
Diseases named in the same sentence as SOX2 in open-access papers (continued):
Sharing a sentence is not in itself a finding about the gene and the disease.
cancer (continued). "SOX2 appears to activate a fundamental mechanism that allows cancer cells to acquire a stem-like phenotype regardless of the original lineage of cancer cells." (PMID 36243874, 2022). "In addition, SOX2 regulates cyclin D1 and CD133 in cancer cells, affecting cancer cell proliferation and generation." (PMID 35562862, 2022). "SPP1 also promotes the expression of cancer stem cell markers such as OCT4 and SOX2." (PMID 35154316, 2022). "In addition, CPZ was able to downregulate the expression of OCT 3/4, SOX2, NANOG, Nestin, OLIG2 and ALDH1A3, universal cancer stem cells genes for GBM." (PMID 33718225, 2021). "In addition, TBL1XR1 is involved in cancer stem cell maintenance through activation of the MEK and PI3K/Akt pathways with a mechanism that involves the stem cell factor SOX2, also a 3q26 gene." (PMID 34436017, 2021). "Cancer stem cell markers also include NANOG, ALDH1, SOX2, OCT4, LGR5, CD44, and CD133; therefore, stemness may be judged by the expression of these markers." (PMID 34725550, 2021). "The small infiltrating cancer nests surrounding CIN 3 margins or the CIN 3-like SCC with deep invasion generally display a decreased SOX2 level locally, and this indicates reduced SOX2 expression during invasive growth." (PMID 33789601, 2021). "Moreover, Tregs are involved in the promotion of cancer stemness as shown in CRC and BC cells, where they induce the expression of the reprogramming factor SRY-box transcription factor 2 (Sox2) via nuclear factor kappa B (NF-kB)-CCL1 signaling." (PMID 34572009, 2021). "Furthermore, inducible expression of SOX2, OCT4 and KLF4 in melanoma cells leads to partial reprogramming of these cancer cells which start exhibiting increased invasion potential and lung colonization." (PMID 33453053, 2021). "Elevated expression of SLUG and TWIST1 significantly increased ALDH activity in PC3 cells, and this activity was significantly decreased by suppression of SOX2, indicating that SOX2 is a critical mediator of SLUG- and TWIST1-mediated cancer stem–like properties." (PMID 34809669, 2021). "HMGA2 suppression decreases expression of the cancer stem cell markers ALDH, SOX2, and Nanog." (PMID 33668453, 2021). "In addition, we introduced a cluster of cancer stemness markers (ES1/2, hESC, iPSC, Nanog, Sox2, Myc, et." (PMID 35071018, 2021). "Binding motifs for many essential TFs, such as RXRA, NFE2L2, ESRRA, IRF2, RELA, ESRRA, SOX2, and SMAD2/3, key TFs that mediate TGFβ signaling in epithelial-mesenchymal transition (EMT) and cancer metastasis, were enriched in common gained or LNC-specific gained enhancers, with some overlapping TFs." (PMID 34294701, 2021). "In addition, the knockdown of LAT1 in A400 and H1299 cells downregulated several cancer stemness genes including BMI1, Sox2, and Oct4." (PMID 34681614, 2021). "Cancer stem-like cells (CSCs) or cancer-initiating cells (TICs) are a subpopulation of cells with high tumorigenic potential, self-renewal ability, and prominent expression of stemness-specific markers such as CD133, Nanog, Sox2, and Oct4." (PMID 34193145, 2021). "The levels of ABCG2, C-Myc, Bmi1, and Sox2 were repressed by the depletion of circNOLC1 in MDA-MB-231 and MDA-MB-468 cells, implying that the inhibition of circNOLC1 attenuates cancer stem cell properties." (PMID 34789263, 2021). "On the other hand, SOX2 is aberrantly expressed in cancer cells, particularly CSC population, and its overexpression is related to poor prognosis, invasion, and metastasis in various cancers." (PMID 34436030, 2021). "Moreover, expressions of stemness genes, such as OCT4, SOX2, and NANOG, are often deployed to measure cancer stemness." (PMID 34760886, 2021). "The upregulation of HIF under hypoxia microenvironment has been shown to induce the expression of known pluripotent stemness factors, such as KLF4, MYC, OCT4, SOX2, and NANOG, to reprogram towards a cancer stem cell (CSC) phenotype and to influence the expansion of CSC populations." (PMID 34798868, 2021).
cancer (continued). "The transformation of fibroblasts to a pluripotent state was possible due to four transcription factors, namely octamer-binding transcription factor 3/4 (Oct-3/4), sex-determining region Y-box 2 (Sox2), Kruppel-like factor 4 (KLF4), and cancer-related Myc gene." (PMID 34873560, 2021). "It was shown that the increase of OCT4, SOX2, and NANOG could enhance the stemness and determine the malignant phenotypes in a wide range of cancers." (PMID 34708581, 2021). "Moreover, the CMCAFs treatment induced the expression of EMT and cancer stemness markers in NOZ and GBC-SD cells, as revealed by reduced E-cadherin expression and increased vimentin, Sox2, CD44, Nanog and Oct4 expression." (PMID 33407730, 2021). "Interestingly, KLF4 and other stemness genes (Oct4, Sox2 and c‐Myc) have proposed as putative targets for HCC therapy because they contributed for maintaining cancer stem cells (CSCs), having strong chemoresistance." (PMID 34114341, 2021). "Furthermore, high levels of SOX2 expression were found to be due to elevated levels of the IGF/IGF-1R signaling downstream proteins Akt and mTOR, which subsequently elevated HCC cancer stemness characteristics." (PMID 33669204, 2021). "Silencing SRI resulted in a decrease in the cancer stem cell markers CD133, CD44, and SOX2." (PMID 34163033, 2021). "Interestingly, exosomes from the PTC cancer stem cell (PTC-CSC) model were transferred beside the transcription factors SLUG and SOX2, the lncRNA MALAT1, and the linc-ROR resulting to the induction of EMT." (PMID 35186709, 2021). "During cancer progression, stemness of cancer cells is maintained by hypoxia through different mechanisms, including enhancement of EMT and the transcriptional induction of stemness related genes (Oct4, POU5F1, Sox2, Nanog, BMI1, Myc and KLF4)." (PMID 33407613, 2021). "Importantly, RT-qPCR analysis showed that ZVI@Ag NPs treatment significantly decreased the expression levels of cancer stemness genes, including OCT4, Nanog, and SOX2." (PMID 34093872, 2021). "Also, overexpression of miR-509-3p decreased expression of SOX2, CD44, and CD133, and enhanced expression of Bax and caspase-3 while repressed Bcl-2 expression in cancer cells." (PMID 34715859, 2021). "ITPR3 and CSC markers such as CD44, SOX2 and OCT4 were enriched in BCa stem cells, which indicated that ITPR3 might play a vital role in maintaining the cancer stemness phenotype." (PMID 33573671, 2021). "In a previous study, it was shown that those subpopulations of cancer cells exhibiting high expression of KLF4 and/or Oct4 and low expression of Sox2 produced much more colonies than subpopulations with high Sox2 expression and lower KLF4 and/or Oct4 expression." (PMID 32138176, 2020). "Pluripotency factors OCT4 and SOX2 and NANOG are markers of cancer stem cells." (PMID 32664372, 2020). "Moreover, compared to the NF-treated cells, the expression of cancer stem cell (CSC) markers CD44, CD133, OCT-4 and SOX2, was significantly upregulated in the CF group." (PMID 32754302, 2020). "Gaining a better insight and comprehensive interrogation into the mechanistic basis of SOX2-mediated generation of CSCs and treatment failure might therefore lead to new therapeutic targets involving CSC-specific anti-cancer strategies." (PMID 30517668, 2020). "SOX2, BMI-1, and PROM1 are cancer stem cells-related genes, and TWISTNB is implicated in EMT." (PMID 32118031, 2020). "In addition, pluripotent stem cell markers SRY box 2 (SOX2), octamer-binding transcription factor 4 (OCT4), and NANOG are often overexpressed in the CSCs of different cancers." (PMID 32244924, 2020). "In sum, various lines of experimental evidence underscore connectivity between SOX2 expression and CSCs in some cancers, although likely not all SOX2-positive cancer cells are CSCs and vice versa." (PMID 31477842, 2020).
cancer (continued). "The inhibition of the NEAT1 expression through the CRISPR-Cas9 method increased the sensitivity of radioresistant MDA-MB-231 cells to radiation and decreased their proliferation, the activity of cancer stem cells, and the expression of stemness genes, including BMI1, Oct4, and Sox2." (PMID 32922184, 2020). "SOX2 also could act as a molecular rheostat in SOX2+ PDAC for their growth, tumorigenicity and responsiveness to anti-cancer drugs." (PMID 30517668, 2020). "The EMT phenotype is common in cancer stem melanoma cell characterized by a positivity for CD133 and PD1 and by CSC intracellular markers comprise enzymes such as aldehyde dehydrogenases (ALDH), and transcription factors such as Sox2 and Klf4." (PMID 32244473, 2020). "At the post-transcriptional level, SOX2 is subjected to regulation by several microRNAs and long non-coding RNAs in cancer cells." (PMID 31748974, 2020). "Previous studies have clarified that miR‐101‐3p regulates various pivotal oncogenes and that downregulation of this miRNA affects cancer cell proliferation, metastasis, drug resistance, and angiogenesis via targeting of several oncogenic targets, e.g. EZH2, STMN1, VHL, SOX2, and DNMT3A." (PMID 31755218, 2020). "SOX2 was barely detected in non-cancerous cells, but strongly expressed in the nucleus of cancer cells." (PMID 33089188, 2020). "Notably, pterostilbene exhibited a greater inhibitory effect against HeLa cancer stem-like cells than resveratrol through more potent inhibition of the expression levels of stemness markers, such as CD133, Oct4, Sox2, and Nanog, as well as STAT3 signaling." (PMID 31935877, 2020). "Here we provide a comprehensive review of the current knowledge on SOX2 protein modifications, their proposed relationship to the PI3K/AKT pathway, and regulatory influence on SOX2 with regards to stemness, reprogramming, and cancer." (PMID 31477842, 2020). "By multivariate survival analysis, Sox2 was a robust pejorative prognostic factor (HR = 1.48, 95% CI 1.04–2.11, p = 0.0292), independent of cancer stage at diagnosis, and independent of AR, whose prognostic value was favorable (p < 0.0001 for the model)." (PMID 33553286, 2020). "A qPCR analysis also revealed elevated expression of the cancer stemness-related genes MMP2, MMP9, Nanog and SOX2, suggesting that NPC43 PD_R cells may have acquired an increase in cancer stemness." (PMID 33243298, 2020). "CSCs drive cancer initiation, progression, metastasis, recurrence and drug resistance, and express Nanog, CD133, CD90, SOX2, EpCAM, CD44, Klf4 and Oct4, some of which may functionally support liver CSC phenotypes like invasiveness and chemoresistance." (PMID 33343368, 2020). "PAA reduced Nanog, Sox2, Oct4, and CD44 gene transcripts of cancer cells." (PMID 33202749, 2020). "We have also found increased β-catenin, SOX2 and GSK-3β protein expression between Caki-1 DC and Caki-1WT, which could suggest cancer stem-cell-like (CSC) and epithelial-mesenchymal transition (EMT) characteristics in Caki-1 DC." (PMID 32041631, 2020). "Cancer stem cells exhibit high expression of OCT4, NANOG and SOX2, which represent their markers." (PMID 32664372, 2020). "SOX2 and OCT4, along with other induced pluripotent stem cell markers KLF4, NANOG, and c-MYC, regulate stemness in CSCs and have been used them to characterize CSCs in other cancer types." (PMID 33147716, 2020). "Interestingly, SOX4 and SOX2 proteins only distantly relate within the SOX family, but the two proteins show nearly overlapping occurrence in human cancers." (PMID 31477842, 2020). "Data showed that SOX2 expression was not correlated with cancer-specific survival (CSS) of CRC in three studies with 855 patients (HR = 1.18, P=0.667) but was correlated with worse overall survival (OS) in two studies with 536 patients (P < 0.05)." (PMID 32104175, 2020).
cancer (continued). "Hypoxia signalling can induce HIF-dependent expression of known pluripotent factors, such as KLF4, MYC, OCT4, SOX2, and NANOG, which have an important role in the dedifferentiation process under hypoxic conditions, inducing cancer stemness and repressing cancer cell differentiation." (PMID 33339101, 2020). "By further confirmation using qRT-PCR, the transcription of the reprogramming factors (NANOG, OCT4, and SOX2) was enhanced by CENPW silencing in HCC cells, implying the possibility of reprogramming into cancer stem cells which characterized by inhibition of cell proliferation and metabolic changes." (PMID 32635817, 2020). "Indeed, knockdown of USP4 in the cancer cell lines D121, LLC, H1299, and HCC827 increased expression of the stemness genes Oct4, Sox2, Nanog, KLF4, ABCG2, and ALDH1 in different degree in different cell lines as measured by RT-qPCR." (PMID 31936290, 2020). "Cancer stem cell markers OCT4 and SOX2 were tracked quantitatively." (PMID 32111825, 2020). "In addition, western blotting revealed that overexpression of MPC1 decreased the level of cancer stem cell (CSC) markers, including NANOG, OCT4, and SOX2 in LAC cells, while knockdown of MPC1 increased the level of these markers." (PMID 30770798, 2019). "In conclusion, our study suggests that SOX2 can be a direct downstream target gene of hsa-miR-590-3p in HCC implying that hsa-miR-590-3p can directly affect the self-renewal and self-maintenance of cancer cells." (PMID 31781476, 2019). "SOX2 gene mapping at 3q26 is frequently amplified in OSCC and other cancers." (PMID 31640140, 2019). "Stem cells, including cancer stem cells (CSCs), are pluripotent and capable of self-renewal, like induced pluripotent stem (iPS) cells induced by the transcription factors Oct3/4, Sox2, c-Myc, and Klf4 or OCT4, SOX2, NANOG, and LIN28." (PMID 31653034, 2019). "Furthermore, knockdown of PKM2 combined with IR markedly reduced the expression of several cancer stem cell biomarkers in vitro, including NANOG, OCT4, SOX2, and Bmi1." (PMID 31114449, 2019). "In our work, we think that MYC can be regulated by both METTL3/IGF2BP2 axis and SOX2 respectively, which might partially explain the elevated expression of MYC in various human cancers." (PMID 31230592, 2019). "With regards to known cancer drivers, 24 showed alterations, including the oral cell lineage transcription factors TP63 (amplified, 21.94%) and SOX2 (amplified, 20.97%), CDKN2A, CCND1 (amplified, 24.27%), PIK3CA (amplified, 20.97%) and EGFR (amplified, 10.67%)." (PMID 31703248, 2019). "Interestingly, we found that cancer stem cell markers (CD44, Nanog, Sox2) were overexpressed in LNCaP DocR and CWR22Rv1 DocR cells compared to their parental cells." (PMID 30621625, 2019). "Overexpression of mda-9 in the non-stem cancer cells of DU-145 and PC3-ML also led to an approximately 2–4-fold increase in PCSCs as well as self-renewal associated genes (Nanog ~13–22-fold, Sox2 ~2–6-fold, Oct4 ~6.8–15-fold)." (PMID 31878027, 2019). "Furthermore, simultaneous expressions of YB-1 and the other four (SOX2, POU3F2, OCT-4, and OLIG1) or five (SOX2, SALL2, OCT-4, POU3F2, and Bmi-1) transcription factors in YB-1 knockout cancer stem cells restored the stemness of YB-1 knockout cancer stem cells." (PMID 31375149, 2019). "In particular, patients carrying SOX2-expressing dysplastic lesions exhibited a significantly higher cancer incidence than those with negative expression." (PMID 30823625, 2019). "Cancer stem cells exhibit ESC-like signatures that include activation of the oncogene c-MYC and similar alterations to important loci responsible for the genesis of pluripotency such as: SOX2, DNMT1, CBX3 and HDAC1." (PMID 31324166, 2019). "First, we found that transient treatment of Doc for 2 days could increase levels of cancer stem cell markers including CD44, Nanog and Sox2 in both LNCaP cells and CWR22Rv1 cells." (PMID 30621625, 2019).
cancer (continued). "Furthermore, mRNA and protein expression analysis demonstrated that stem-related markers (Nanog, Oct4, Sox2, and C-myc) were markedly increased in CD133− cancer cells following 7 days coculture with irradiated feeder cells." (PMID 31558702, 2019). "Importantly, shNEAT1 reduced stem cell populations such as CD44+/CD24−, ALDH+, and SOX2+, implicating that NEAT1 was closely related to cancer stemness in TNBC." (PMID 30894512, 2019). "The factors OCT4, Nanog, SOX2, Klf4, C-MYC, and Lin28 play crucial roles in cancer progression." (PMID 31921617, 2019). "Five of 18 patients (28%) with anti-Hu antibody associated LE (4 SCLC, 1 no cancer detected) and one further LE patient with GABAb antibodies and SCLC were positive for SOX2 antibodies." (PMID 30445363, 2019). "Further results from immunoblot suggest that CHTOP knockdown not only decreased the protein expressions of two representative surface markers of cancer stem cell (CD44 and ALDH1) but also inhibited the protein expressions of two important transcriptional makers of cancer stem cell (SOX-2 and NANOG)." (PMID 30910850, 2019). "Likewise, there is a strong correspondence between SOX2 and ST6GAL1 CNGs in the NCI-60 panel of established cancer cell lines." (PMID 31610800, 2019). "Furthermore, identification of protein markers such as ALDH1A1, Sox2, CD44, Oct4, CD133, CD24, and Nanog, etc. have been vital in studying CSCs in cancer research." (PMID 31530793, 2019). "Similarly, OCT4, SOX2, and NANOG increased the ability to form spheres indicating a role in obtaining cancer stem cell properties." (PMID 31885625, 2019). "iHMGB1+ resulted in significant upregulation of mRNA and protein expression of stem cell markers (Oct4, Sox2, and Nanog) in CD133− cancer cells, their sphere-forming ability, as well as CD133+ cell percentage 7 days post coculture, which were comparable to 250–300 ng/mL rhHMGB1." (PMID 31558702, 2019). "Inhibition of Ezh2 could reverse Doc-induced expression of Nanog, Sox2, CD44 and Doc-induced enriched population of cancer stem cells." (PMID 30621625, 2019). "Moreover, cancer stemness related genes such as CD44, CD133, LGR5, LSD1, OCT4, Sox2 and Sox9 were co-upregulated with LETM1 in A549 cells." (PMID 31500591, 2019). "Furthermore, the ability of α‐Mangostin to suppress the expression of pluripotency maintaining genes Oct4, Sox2, KLF4 and c‐Myc suggest that it can directly control cancer stem cells, proliferation, pluripotency and self‐renewal." (PMID 30712329, 2019). "Also, evidence has revealed that the SOX2 and NANOG are critical factors in conferring certain CSC properties to cancer cells such as self-renewal, metastasis and drug resistance." (PMID 29963272, 2018). "Western blot assay showed that silence of PCAT3 or PCAT9 decreased the protein levels of OCT4, SOX2, NANOG and VEGF in LNCaP and 22Rv1 cells, suggesting that PCAT3 and PCAT9 may modulate the properties of angiogenesis and cancer stem cells in PCa." (PMID 29552304, 2018). "Activated Hh could increase Gli expression and enhance SRY-box 2 (Sox2) and Octamer-binding transcription factor 4 (OCT4) expression to regulate cancer stem cell maintenance." (PMID 29734730, 2018). "In addition, the protein expression levels of the genes related to cancer stemness, including NANOG and SOX2 were significantly downregulated in RIF1-knockdown EOC cells and were upregulated in RIF1-overexpressed EOC cells." (PMID 30075819, 2018). "Interestingly, among the genes that are regulated by TRPM7, SOX2, CD133 and KLF4 are cancer stemness markers." (PMID 30477473, 2018). "In contrast to our findings, previous studies in human cancer as well as cancer cell lines have demonstrated a positive correlation between Sox2ot and Sox2 in certain but not all cell types investigated." (PMID 29321583, 2018). "SOX2 and NANOG are transcription factors and biomarkers for cancer stem cells (CSCs)." (PMID 29963272, 2018).